RNU7-49P (RNA, U7 small nuclear 49 pseudogene)
Synonyms: U7.49
Gene: Small nuclear RNA gene on chromosome 11 (14,478,892 to 14,478,953, forward strand). Ensembl gene ENSG00000251991.
Homologues: Orthologues: macaque U7 (92% identical), tropical clawed frog U7 (60% identical), tropical clawed frog U7 (58% identical), tropical clawed frog U7 (56% identical), tropical clawed frog U7 (55% identical), tropical clawed frog U7 (53% identical), tropical clawed frog U7 (52% identical), tropical clawed frog U7 (50% identical). Paralogues in human: RNU7-14P (87% identical), RNU7-4P (87% identical), RNU7-7P (87% identical), RNU7-128P (85% identical), RNU7-2P (85% identical), RNU7-3P (85% identical), RNU7-47P (85% identical), RNU7-81P (85% identical), RNU7-8P (85% identical), RNU7-10P (84% identical), RNU7-11P (84% identical), RNU7-147P (84% identical), and 143 more.